ADA (adenosine deaminase)
Diseases named in the same sentence as ADA in open-access papers (continued):
Sharing a sentence is not in itself a finding about the gene and the disease.
cyst (2 papers, 2012 to 2025). A sac-like closed membranous structure that may be empty or contain fluid or amorphous material. "The cyst was aspirated, yielding approximately 600 mL of clear, light-yellow fluid, which was sent for cytological and adenosine deaminase (ADA) analysis." (PMID 41040760, 2025).
cystic fibrosis (2 papers, 2020 to 2023). Autosomal recessive disorder caused by pathogenic variants in the CFTR gene (cystic fibrosis transmembrane conductance regulator), which encodes a chloride and bicarbonate channel expressed in epithelial cells, and follow the diagnosis criteria. "In this study, the serum ADA activity was analyzed in groups of individuals with altered nutritional status: young adult patients with Nervous Anorexia, overweight children and children suffering cystic fibrosis." (PMID 33362679, 2020).
Dengue (2 papers, 2015 to 2024). "D7 protein inhibits dengue virus infection, whereas a factor Xa–directed anticlotting serpin-like protein and an adenosine deaminase increase the dengue viral burden in human epidermal keratinocytes in vitro." (PMID 39121194, 2024).
endometriosis (2 papers, 2019 to 2020). The growth of functional endometrial tissue in anatomic sites outside the uterine body. "The co-administration of AK inhibitors, such as ABT-702, with ADA inhibitors at lower doses as adjuvants, seems to be a suitable strategy for analgesia in endometriosis patients, but exhaustive prior safety studies are required." (PMID 33198179, 2020). "In relation to the ATP metabolism, knowing the levels of ADA, the soluble enzyme that hydrolyses the extracellular adenosine to control the immunosuppressive milieu, is key to understanding what is happening in endometriosis." (PMID 31698766, 2019).
fibrosis (2 papers, 2010 to 2019). the formation of excess fibrous connective tissue in an organ or tissue in a reparative or reactive process. "ADA-deficient mice are characterized by chronically enhanced tissue adenosine levels and collagen content as well as increased levels of pro-fibrotic mediators like TGF-β, α-SMA, CTGF and IL-13, and are therefore used as paradigm of adenosine-induced fibrosis in the lung and the skin." (PMID 31623231, 2019).
Giardia infection (2 papers, 2012 to 2024). "An advantage for the treatment of giardiasis is that the phosphorylated form of the drug is protected against adenosine deaminase, which increases the chances that it can reach the site of the parasites intact." (PMID 39607702, 2024).
gram-positive bacterial infections (2 papers, 2016 to 2019). Infections caused by bacteria that retain the crystal violet stain (positive) when treated by the gram-staining method. "In this retrospective study, we aimed to evaluate the diagnostic accuracy of pleural adenosine deaminase in discrimination between Gram-negative and Gram-positive bacterial infections of the pleural space prior to selecting antibiotics." (PMID 27276396, 2016). "Pleural effusion adenosine deaminase is a helpful alternative biomarker for early and quick discrimination of Gram-negative from Gram-positive bacterial infections of the pleural space, which is useful for the selection of antibiotics." (PMID 27276396, 2016). "In particular, the optimal cutoff value of PE ADA activity for discriminating between Gram-negative and Gram-positive bacterial infections of the pleural space was determined." (PMID 27276396, 2016). "In our study, the PE ADA level was lower in patients with Gram-negative bacterial infection compared with those with Gram-positive bacterial infection." (PMID 27276396, 2016).
hyperthyroidism (2 papers, 2015 to 2017). Overactivity of the thyroid gland resulting in overproduction of thyroid hormone and increased metabolic rate. "This action of ADA inhibition developed in both thyroid states, but it was greater in hyperthyroidism." (PMID 25877465, 2015). "It is especially interesting that this action of ADA inhibition is stronger in hyperthyroidism, a condition that places an extra burden on the heart with a simultaneous reduction of some A1 receptor functions." (PMID 25877465, 2015). "Nevertheless, consistent with our previous observation, this efficiency-enhancing effect of ADA inhibition is stronger in hyperthyroidism." (PMID 25877465, 2015). "Thus, the enhancement of endogenous protective ability of the heart by means of ADA inhibition seems to be an especially promising possibility in hyperthyroidism." (PMID 25877465, 2015). "Second, ADA inhibition enhances the A1 adenosinergic direct negative inotropy even in the euthyroid state, although to a less extent than in hyperthyroidism." (PMID 25877465, 2015). "First, as the efficiency enhancing effect of ADA inhibition is stronger in the hyperthyroid atria, no conclusion is worth being drawn from the greater cx in the presence of DCF in hyperthyroidism." (PMID 25877465, 2015).
Ileitis (2 papers, 2014 to 2023). "CD73 suppression and adenosine deaminase upregulation rescued post-inflammatory ileitis through neuromodulation, as adenosine mediated both anti-inflammatory (via A2A) and pro-inflammatory (via A1 and A2B) activities." (PMID 36982618, 2023).
infertile (2 papers, 2020 to 2025). "MR analysis using the inverse variance weighted (IVW) method indicated that insomnia, subjective long sleep duration, and high sleep efficiency were associated with increased levels of oncostatin‐M, artemisinin, and adenosine deaminase, all of which are implicated in infertility." (PMID 40525280, 2025). "UA levels (P=0.034) and 5'-NU activity (P=0.046) were significantly lower but ADA (P=0.05) and XO (P=0.015)activities were significantly higher in infertile men than in healthy men." (PMID 31710193, 2020). "MR results revealed genetic correlations between abnormal ADA, artemin, OSM, caspase 8, CXCL5, interleukin‐18, and LIFR levels and infertility." (PMID 40525280, 2025).
influenza (2 papers, 2016 to 2025). An acute viral infection of the respiratory tract, occurring in isolated cases, in epidemics, or in pandemics; it is caused by serologically different strains of viruses (influenzaviruses) designated A, B, and C, has a 3-day incubation period, and usually lasts for 3 to 10 days. "In women who received influenza vaccination (n = 62), only the relative concentration of ADA (its deficiency is associated with lack of cellular and humoral immunity) was significantly higher although the effect size was very minor." (PMID 40949320, 2025).
injury (2 papers, 2015 to 2025). Damage inflicted on the body as the direct or indirect result of an external force, with or without disruption of structural continuity. "Although ADA blockers have been reported to decrease radical generation and prevent postischemic heart injury 5, there were controversies regarding the cardioprotection of ADA blockers." (PMID 25388908, 2015).
ischemia (2 papers, 2022 to 2024). A hypoperfusion of the BLOOD through an organ or tissue caused by a PATHOLOGIC CONSTRICTION or obstruction of its BLOOD VESSELS, or an absence of BLOOD CIRCULATION. "In hepatic ischemia/reperfusion processes, ozone preserved adenosine levels and maintained, at the level of the control group, the activity of the enzyme adenosine deaminase, which biotransforms the nucleoside into inosine." (PMID 38543177, 2024).
joint diseases (2 papers, 2010 to 2025). "ADA levels in tubercular joint effusions ranged between 46 and 156 with a median level of 88, and in non- tubercular joint effusions it ranged between 25 and 32.6 with a median value of 27.2." (PMID 21629524, 2010).
Lesch–Nyhan disease (2 papers, 2022 to 2023). "The general importance of purine metabolism in the brain is additionally emphasized by other diseases that are associated with abnormal purine metabolism such as HPRT deficiency (Lesch-Nyhan syndrome) and ADA deficiency." (PMID 37546759, 2023). "Among them are Lesch–Nyhan disease, later shown to be caused by deficient hypoxanthine-guanine phosphoribosyltransferase (HPRT) activity, adenosine deaminase (ADA) deficiency and purine nucleoside phosphorylase (PNP) deficiency." (PMID 35955904, 2022).
lymphoproliferative disorders (2 papers, 2010 to 2022). "ADA is increased in effusions resulting from infections, rheumatological diseases, and lymphoproliferative disorders, including TB, and especially peritoneal TB, due to the increase in T-cell differentiation in response to the TB antigen." (PMID 36340021, 2022).
malnutrition (2 papers, 2020 to 2025). Inadequate nutrition resulting from poor diet, malabsorption, or abnormal nutrient distribution. "The highest risk of malnutrition, identified in 133 patients, was also significantly associated with elevated ADA levels (F = 3.378; p = 0.036; R = 0.153; R2 = 0.024; η = 0.179; η2 = 0.032)." (PMID 40572784, 2025). "In our study, there was a significant increase in ADA in patients at risk of malnutrition and malnourished patients." (PMID 33362679, 2020).
myelogenous leukaemias (2 papers, 1976 to 2022). "ADA was elevated in blasts of patients with acute lymphocytic and myelogenous leukaemias but the ranges of activities per cell were so similar that ADA assay is unlikely to be of major help in distinguishing the two diseases." (PMID 1063590, 1976).
myocardial infarction (2 papers, 2015 to 2025). Gross necrosis of the myocardium, as a result of interruption of the blood supply to the area, as in coronary thrombosis. "Serum adenosine deaminase activity is notably reduced in patients with CAD, particularly in cases of myocardial infarction." (PMID 40459864, 2025).
nephrotic syndrome (2 papers, 2010 to 2020). A collection of symptoms that include severe edema, proteinuria, and hypoalbuminemia; it is indicative of renal dysfunction. "Enhancing adenosine deaminase activity in podocytes is not sufficient to render mice sensitive to PAN in terms of nephrotic syndrome." (PMID 20649959, 2010).
neuropathy (2 papers, 2022 to 2024). A disorder affecting the nervous system that manifests with pain, tingling, numbness, and/or muscle weakness. "Third, we did not analyze the relationship between serum ADA levels and the severity of DPN evaluated by the scoring of DPN signs/symptoms in our present study, such as the Michigan Neuropathy Screening Instrument (MNSI) and the modified Toronto Clinical Neuropathy Scale (mTCNS)." (PMID 36267565, 2022).
neutropenia (2 papers, 2021 to 2025). A decrease in the number of neutrophils found in the blood. "Recently, intermittent or persistent low neutrophil counts in peripheral blood were identified in 13 of 20 ADA-deficient infants, with the most severe neutropenia occurring during infections." (PMID 34777360, 2021). "In conclusion, our study provides further evidence that ADA is required for hematopoietic and neutrophil development and that the neutropenia exhibited by ADA-deficient patients is directly associated with the enzyme defect." (PMID 34777360, 2021). "Moreover, neutrophil abnormalities with marked neutropenia, hyperlobular and pyknotic neutrophils have been previously reported among ADA-deficient patients who received allogeneic or autologous gene-corrected hematopoietic stem cell (HSC)." (PMID 34777360, 2021). "Additionally, neutropenia and impaired neutrophil function have been reported among ADA-deficient patients." (PMID 34777360, 2021). "Infants in this study had mean trough plasma ADA levels ranging from 83.2 to 264.2 μmol/mL, which was generally well tolerated except for two cases of thrombocytosis, one case of neutropenia and one case of hypercalcemia." (PMID 40140214, 2025).
oral cancer (2 papers, 2021 to 2022). "Some publications indicated that ADA activity is different in healthy controls and patients with oral cancers, though the results are contradictory." (PMID 35967411, 2022).
osteoarthritis (2 papers, 2016 to 2024). A noninflammatory degenerative joint disease occurring chiefly in older persons, characterized by degeneration of the articular cartilage, hypertrophy of bone at the margins and changes in the synovial membrane. "Higher levels of adenosine deaminase (ADA) were associated with septic arthritis (infection-related inflammation), rather than crystal-induced or osteoarthritis." (PMID 39219968, 2024). "Higher levels of ADA were associated with septic arthritis (infection-related inflammation), rather than crystal-induced or osteoarthritis." (PMID 39219968, 2024).
pancreatic cancer (2 papers, 2016 to 2018). "The enzyme ADAR2 (adenosine deaminase that acts on RNA) is important for RNA editing and pancreatic cancer progression." (PMID 29682326, 2018). "Serum ADA levels increase in pancreatic disorders, especially in pancreatic cancer; therefore it may be used as a serum marker for the diagnosis of pancreatic cancer." (PMID 28330104, 2016).
pulmonary arterial hypertension (2 papers, 2017 to 2021). Pulmonary arterial hypertension (PAH) is a group of diseases characterized by mean pulmonary artery pressure >20 mmHg and elevated pulmonary arterial resistance leading to right heart failure. "Low levels in PAH may also be explained by increased activity of the adenosine deaminase in the pulmonary circulation, which was found in rats with hemolysis-associated pulmonary hypertension." (PMID 29255415, 2017).
purine metabolism disorder (2 papers, 2021 to 2023). "In the presented case, genetic tests revealed homozygous pathogenic mutations in ADA gene that eventually led to purine metabolism disorder." (PMID 34502390, 2021). "Adenosine deaminase (ADA) deficiency, owing to ADA gene mutation, results in the purine metabolism disorder." (PMID 34502390, 2021). "Purine metabolism disorders caused by ADA deficiency might influence various tissues by currently unknown mechanisms." (PMID 34502390, 2021).
pyometra (2 papers, 2020). "This fact would indicate that ADA in saliva can increase in inflammatory conditions in dogs, in line with a previous report made in bitches with pyometra, which presented higher salivary tADA values than healthy dogs." (PMID 33046093, 2020). "Saliva composition is also known to be modulated in canine pyometra because increased and decreased concentrations of adenosine deaminase and adiponectin, respectively—biomarkers related to of inflammation—were found in bitches with pyometra in comparison to healthy ones." (PMID 32596263, 2020).
septic arthritis (2 papers, 2021 to 2024). "Specifically, based on the source, adenosine deaminase is useful in differentiating septic arthritis from rheumatoid and crystal-induced arthritis." (PMID 39219968, 2024). "To sensitively, specifically and quickly diagnose septic arthritis, several synovial fluid host-specific biomarkers, including interleukin-6, adenosine deaminase, alpha-defensin, leukocyte esterase, and calprotectin, were evaluated." (PMID 34656157, 2021). "Synovial fluid adenosine deaminase (ADA) has been identified as a useful marker in differentiating septic arthritis from rheumatoid and crystal-induced arthritis, aiding in accurately diagnosing septic arthritis in these patients." (PMID 39219968, 2024).
sickle cell disease (2 papers, 2019). Sickle cell anemias are chronic hemolytic diseases that may induce three types of acute accidents: severe anemia, severe bacterial infections, and ischemic vasoocclusive accidents (VOA) caused by sickle-shaped red blood cells obstructing small blood vessels and capillaries. "Currently, clinical trials of gene therapy with lentiviral vector systems are having a profound impact on several monogenetic diseases, including ADA-SCID, SCID-X1, ALD, MLD, X-CGD, WAS, β-thalassemia, and sickle cell disease." (PMID 30875857, 2019).
T cell deficiency (2 papers, 2014 to 2024). "In particular, the ATO system does not allow to identify forms of severe T cell deficiency due to intrathymic migration defects nor late defects of T cell development (beyond the DP stage) or SCID due to adenosine deaminase (ADA) deficiency." (PMID 39167072, 2024).
thyroid autoimmune diseases (2 papers, 2024 to 2025). "ADA, a key enzyme involved in purine metabolism and immune system regulation, has been associated with thyroid autoimmune diseases at the transcriptional level." (PMID 38774877, 2024).
uveitis (2 papers, 2021 to 2022). An inflammatory process affecting a part of or the entire uvea. "Among the patients with a history of AAU who were uveitis-free during the 2 years before TNFis initiation, ETN was also associated with a higher adjusted HR than was ADA (AAU history (+): HR 1.99, 95% CI 1.58–2.50, p < 0.001; AAU history (−): HR 2.82, 95% CI 1.92–4.13, p < 0.001)." (PMID 35160082, 2022). "Most international studies have focused on ADA and IFX, which are the most commonly recently employed biological agents for patients with uveitis." (PMID 34795583, 2021).
Ventriculomegaly (2 papers, 2009 to 2017). An increase in size of the ventricular system of the brain. "Moreover, ventriculomegaly was also observed in mice lacking the enzyme, adenosine deaminase, which degrades adenosine." (PMID 19725982, 2009).
visceral leishmaniasis (2 papers, 2016 to 2020). A severe form of leishmaniasis characterized by irregular bouts of fever, substantial weight loss, swelling of the spleen and liver, and anemia (which may be serious). "Here, our study is an attempt to investigate the serum ADA activities of patients with visceral leishmaniasis (VL), post kala-azar dermal leishmaniasis (PKDL) and endemic asymptomatic subjects in comparison with healthy control." (PMID 27186641, 2016). "Since cell-mediated immune responses play a paramount role in the pathogenesis and healing of the visceral leishmaniasis, therefore, the present study was undertaken to evaluate the serum ADA activity in different pathological conditions." (PMID 27186641, 2016). "So, we presume that in lymphocyte depleted condition, the elevated serum ADA might be contributed by monocytes during visceral leishmaniasis." (PMID 27186641, 2016).
WHIM syndrome (2 papers, 2023). "The risk of type 1 diabetes (T1D) is higher in patients with IPEX (FOXP3, forkhead box P3), WHIM syndrome, autoimmune polyglandular syndrome type 1 (APS type 1 due to AIRE mutation), CTLA4 mutation, deficiency of LRBA, milder forms of ADA deficiency, and STAT1 GOF." (PMID 37102642, 2023).
acne (1 paper, 2018). An inflammatory process of the sebaceous glands which is characterized by comedones, nodules, papules and/or pustules on the skin. "In addition, immunostaining demonstrated overexpression of S100P and FDXR but mild downexpression of K10 in acne lesion, while ADA expression was absent in both acne lesion and normal skin." (PMID 29850553, 2018). "However, ADA immunoreactivity was negative in both acne lesion and normal skin." (PMID 29850553, 2018).
acute respiratory distress syndrome (1 paper, 2023). Progressive and life-threatening pulmonary distress in the absence of an underlying pulmonary condition, usually following major trauma or surgery. "Deoxycoformycin (dCF), a potent and tightly binding ADA inhibitor was proposed to balance the signals through adenosine receptors as beneficial in late stage acute respiratory distress syndrome." (PMID 37685949, 2023).
adult T-cell leukemia (1 paper, 2022). "Some examples, including ADA for adult T-cell leukemia (ATL), CD3D for T1DM and EPCAM for hepatitis C (HC), are known target–disease associations, indicating that our proposed method can accurately predict known therapeutic indications." (PMID 35758779, 2022).
AIDS encephalopathy (1 paper, 2011). "HIV-1 Envs ADA, JR-FL and JR-CSF were cloned roughly two decades ago from a monocytotropic virus, and from the frontal lobe and cerebrospinal fluid of a patient with severe AIDS encephalopathy, respectively." (PMID 21738637, 2011).